SMIM14 (small integral membrane protein 14)
Synonyms: C4orf34; FLJ13289
Tractability: Antibody: UniProt predicts a signal peptide or a membrane-spanning region. PROTAC: ubiquitination databases record sites on it.
Gene: Protein-coding gene on chromosome 4 (39,546,336 to 39,639,088, reverse strand). Ensembl gene ENSG00000163683.
Subcellular location: Endoplasmic reticulum membrane
Gene Ontology:
Molecular function: protein binding
Cellular component: endoplasmic reticulum; endoplasmic reticulum membrane
Genetic constraint (gnomAD): Loss-of-function variants: 3 observed, 4.2 expected, observed/expected ratio (o/e) 0.71, 90% interval 0.32 to 1.67. That is too few expected variants to judge how well the gene tolerates losing a copy. Missense variants: 44 observed, 60.95 expected, observed/expected ratio (o/e) 0.72, 90% interval 0.57 to 0.93. Synonymous variants: 14 observed, 22.07 expected, observed/expected ratio (o/e) 0.63, 90% interval 0.42 to 0.99.
Homologues: Orthologues: macaque SMIM14 (99% identical), chimpanzee SMIM14 (98% identical), mouse Smim14 (90% identical), pig SMIM14 (74% identical), tropical clawed frog smim14 (72% identical), zebrafish smim14 (71% identical), Caenorhabditis elegans smim-14 (37% identical), Drosophila melanogaster CG13585 (33% identical).
Diseases named in the same sentence as SMIM14 in open-access papers:
SMIM14 is named in the same sentence as 6 diseases in open-access papers, as found by Europe PMC text mining. Sharing a sentence is not in itself a finding about the gene and the disease. The quoted sentences say what the papers report.
frontotemporal lobar degeneration (1 paper, 2022). "Further, an extensive RNA sequencing study in the frontal cortex tissue of patients with frontotemporal lobar degeneration revealed a decreased differential expression of the small integral membrane protein 14 gene (SMIM14)." (PMID 35955622, 2022).
SMIM14 also shares sentences with these, for which no sentence is quoted: cancer (1 paper); Hypertension (1); schizophrenia (1); tumor (1); viral infections (1).